TMEM67 (transmembrane protein 67)
Description:
Required for ciliary structure and function. Part of the tectonic-like complex which is required for tissue-specific ciliogenesis and may regulate ciliary membrane composition (By similarity). Involved in centrosome migration to the apical cell surface during early ciliogenesis. Involved in the regulation of cilia length and appropriate number through the control of centrosome duplication. Is a key regulator of stereociliary bundle orientation (By similarity). Required for epithelial cell branching morphology. Essential for endoplasmic reticulum-associated degradation (ERAD) of surfactant protein C (SFTPC). Involved in the negative regulation of canonical Wnt signaling, and activation of the non-canonical cascade stimulated by WNT5A. In non-canonical Wnt signaling, it may act as ROR2 coreceptor (By similarity).
Synonyms: MKS3; MGC26979; JBTS6; NPHP11; MECKELIN; TNEM67
Tractability: Antibody: UniProt places it where antibodies can reach, with high confidence; UniProt predicts a signal peptide or a membrane-spanning region; its Gene Ontology location is reachable by antibodies, with medium confidence. PROTAC: ubiquitination databases record sites on it.
Gene: Protein-coding gene on chromosome 8 (93,754,844 to 93,819,234, forward strand). Ensembl gene ENSG00000164953.
Subcellular location: Cell membrane; Endoplasmic reticulum membrane; Cell projection, cilium; Cytoplasm, cytoskeleton, cilium basal body
Pathways (Reactome):
Organelle biogenesis and maintenance: Anchoring of the basal body to the plasma membrane
Gene Ontology:
Molecular function: filamin binding; protein binding
Biological process: cilium assembly; ERAD pathway; negative regulation of centrosome duplication; non-canonical Wnt signaling pathway; protein localization to ciliary transition zone
Cellular component: centrosome; ciliary membrane; ciliary transition zone; cytoplasmic vesicle membrane; endoplasmic reticulum membrane; plasma membrane; MKS complex; cilium
Genetic constraint (gnomAD): Loss-of-function variants: 60 observed, 68.94 expected, observed/expected ratio (o/e) 0.87, 90% interval 0.71 to 1.08. The upper end of that interval is the gene's LOEUF score, 1.08, which puts it in group 4 of 6, group 1 being the genes least tolerant of losing a copy. Missense variants: 640 observed, 723.56 expected, observed/expected ratio (o/e) 0.88, 90% interval 0.83 to 0.94. Synonymous variants: 233 observed, 254.3 expected, observed/expected ratio (o/e) 0.92, 90% interval 0.82 to 1.02.
Gene-disease validity (ClinGen):
ClinGen rates the evidence that TMEM67 causes each of these diseases.
ciliopathy (autosomal recessive): Definitive. A genetic disorder of the cellular cilia or the cilia anchoring structures, the basal bodies, or of ciliary function.
Homologues: Orthologues: chimpanzee TMEM67 (99% identical), macaque TMEM67 (96% identical), pig TMEM67 (90% identical), dog TMEM67 (89% identical), rabbit TMEM67 (89% identical), guinea pig TMEM67 (85% identical), mouse Tmem67 (85% identical), rat Tmem67 (84% identical), tropical clawed frog tmem67 (60% identical), zebrafish tmem67 (58% identical), Caenorhabditis elegans mks-3 (26% identical), Drosophila melanogaster CG15923 (23% identical).
Diseases named in the same sentence as TMEM67 in open-access papers:
TMEM67 is named in the same sentence as 67 diseases in open-access papers, as found by Europe PMC text mining. Sharing a sentence is not in itself a finding about the gene and the disease. The quoted sentences say what the papers report.
ciliopathies (34 papers, 2011 to 2025). "MKS3 (Tmem67) is a central player, causative in all three major ciliopathies, Meckel-Gruber syndrome, Nephronophthisis and Joubert-Syndrome." (PMID 38110903, 2023). "In this study, we have focussed on TMEM67 (also called MKS3), which is associated with several ciliopathies including Meckel Syndrome (OMIM #607361), COACH Syndrome (OMIM #216360) and Joubert Syndrome (OMIM #610688)." (PMID 34964473, 2022). "The utility of the nematode approach to interpreting human gene variants goes well beyond TMEM67 and the ciliopathy gene class." (PMID 34964473, 2022). "In this study, we explore the use of an animal model (Caenorhabditis elegans) for in vivo interpretation of missense VUS alleles of TMEM67, a cilia gene associated with ciliopathies." (PMID 34964473, 2022). "TMEM67 gene, encoding the transmembrane protein meckelin, is responsible of a group of diseases called human ciliopathies." (PMID 32928283, 2020). "Mutation or dysregulation of Cc2d2a, Tmem67, Kif7 plus Tmem107 and Topors, are known to cause ciliopathies." (PMID 30260431, 2018). "Among them, Tmem67, Cc2d2a and Kif7 mRNAs were linked to Joubert syndrome and Meckel Gruber syndrome, both belonging to the ciliopathy family." (PMID 30260431, 2018). "As mutations in TMEM67 are associated with ciliopathy phenotypes in JSRDs16, exploration of the structure or function of the cilia in COACH syndrome is warranted." (PMID 28860541, 2017). "The phenotypic heterogeneity of MKS3 abnormalities observed in patients with TMEM67 mutations has significant overlaps at each end of its spectrum with two other ciliopathies–Joubert syndrome and nephronophthisis." (PMID 28487520, 2017). "Mutations in TMEM67 (MKS3) cause a range of human ciliopathies, including Meckel-Gruber and Joubert syndromes." (PMID 26035863, 2015). "CC2D2A- and TMEM67-associated ID disorders are ciliopathies, and apart from its established role in chromosome cohesion, SMC3 has been recently shown to be required for Planar Cell Polarity, a process underlying cilium formation." (PMID 24204314, 2013). "Since the submission of this variant classification to the Franklin Community, it has come to our attention that this intronic variant has been detected in trans with another pathogenic TMEM67 variant in two additional fetuses manifesting with a ciliopathy phenotype." (PMID 36221156, 2022). "The observation that affected lambs exhibited a fetal mid-gestational onset of PKD with liver fibrosis and a ductal plate malformation, together with perinatal lethality and mutations in TMEM67, suggests that the syndrome in the affected lambs is a model for the human ciliopathy, MKS3." (PMID 28487520, 2017). "Furthermore, some MKS mutations, such as the TMEM67 p.R440Q missense mutation, are allelic for Joubert syndrome and other ciliopathies." (PMID 23351400, 2012). "TMEM67 and TULP3-associated ciliopathies were frequently associated with ARFI-based liver fibrosis which is in line with previous reports." (PMID 40247009, 2025). "Here, we show that RPGRIP1L is not required for SHH activation or motoneuron lineage commitment in human spinal progenitors and that this feature is shared by another ciliopathy gene, TMEM67." (PMID 40188187, 2025). "Overall, TMEM67 showed one of the widest clinical continuum observed in ciliopathies ranging from early lethality to adults with liver fibrosis." (PMID 32928283, 2020). "The highest intensity points of TMEM67 and TCTN2 occurred at the same axial level as MKS1 and RPGRIP1L, indicating a special axial level accommodating these ciliopathy-associated proteins." (PMID 26365165, 2015). "The transmembrane Frizzled-like receptor Tmem67/MKS-3, a transition zone protein that functionally binds Wnt5a and whose mutations are responsible for the MKS and JBTS ciliopathies, has moreover been located to the PC base of the C. elegans ciliated sensory neurons." (PMID 40661145, 2025).
ciliopathies (continued). "Furthermore, TMEM-218 can be positioned genetically and hierarchically within the MKS module, likely as a peripheral component, similar to MKS-3 (Tmem67), JBTS-14 (Tmem237), and MKS-6 (Cc2d2a), which are all ciliopathy-associated." (PMID 26982032, 2016). "Pulmonary hypoplasia was a consistent finding in the Tmem67−/− embryos and pups, although this is frequently under-reported in human ciliopathies and not considered an essential diagnostic clinical feature of MKS in humans." (PMID 26035863, 2015). "Furthermore, the signature included genes whose mutations are known to cause ciliopathies with dysfunctions of primary cilia (e.g. ARL6, LCA5, TMEM67)." (PMID 22558177, 2012). "At least two polymorphic markers per gene (rs1718031 and rs729386 for NPHP1; rs1041480 and rs2064430 for AHI1; rs2061589 and rs1508595 for CEP290; rs1990637 and rs1946155 for RPGRIP1L; rs1483457 and rs911 for TMEM67) were inconsistent with linkage in Ciliopathy-672." (PMID 22002901, 2011). "The observations of increased Hoxb5 gene expression in the Tmem67−/− cerebellum and increased occupancy of Hoxb5 at the β-catenin promoter therefore provide a mechanistic explanation for increased canonical Wnt/β-catenin signalling in the ciliopathy disease state." (PMID 30931988, 2019). "In C. elegans, the TMEM67 orthologue MKS-3 forms part of the MKS module, along with at least 10 other ciliopathy proteins, whereas the NPHP module consists of just two proteins (NPHP-1, NPHP-4)." (PMID 34964473, 2022). "WES revealed biallelic variation in 3 ciliopathy genes (PKHD1, TMEM67 and IFT172) in 4 clinically unrelated index subjects (3 children and 1 adult), heterozygosity for a known variant in PPOX in one adult index subject, and homozygosity for an unreported splice-site variation in F11R in one child." (PMID 37471416, 2023). "Highlighted Article: TMEM67 is a receptor of non-canonical Wnt signalling, implicating the Wnt5a-TMEM67-ROR2 axis during developmental signalling and disruption in ciliopathy disease state." (PMID 26035863, 2015).
Joubert syndrome (19 papers, 2012 to 2025). Joubert syndrome (JS) is characterized by congenital malformation of the brainstem and agenesis or hypoplasia of the cerebellar vermis leading to an abnormal respiratory pattern, nystagmus, hypotonia, ataxia, and delay in achieving motor milestones. "Other reported orbital lesion in Joubert syndrome due to a pathogenic variant in the same TMEM67 gene includes a case of bilateral opticmeningoceles." (PMID 39027323, 2024). "More than 30 genes causing Joubert syndrome were found, among which TMEM67 was one of the most common genes." (PMID 34356094, 2021). "The parents of the child with Joubert syndrome or with Meckel–Gruber syndrome associated with TMEM67 mutations are at a high, 25% risk of recurrence of this syndrome in subsequent pregnancies (autosomal recessive inheritance)." (PMID 34356094, 2021). "This study confirms the diagnosis of Joubert syndrome in a Vietnamese family and expands the mutational spectrum of TMEM67 sequence variations." (PMID 32000717, 2020). "TMEM67 has been implicated in the pathogenesis of Meckel–Gruber syndrome, Joubert syndrome, and COACH syndrome (cerebellar vermis hypo/aplasia, oligophrenia, congenital ataxia, coloboma and congenital hepatic fibrosis)." (PMID 29379777, 2017). "Mutations in TMEM67 in Joubert syndrome are the most frequently associated with kidney disease, whereas mutations in CEP290 were most likely to give retinal, renal, and brain phenotypes." (PMID 29379777, 2017). "The first proband with TMEM67 mutations suffers from polycystic kidney and brain anomalies, which prenatally were diagnosed as Meckel–Gruber syndrome, but postnatally were clinically verified as Joubert syndrome." (PMID 34356094, 2021). "However, usually, nephronophthisis and cystic dysplasia spectrum were observed in the majority of cases of Joubert syndrome with TMEM67 mutations." (PMID 34356094, 2021). "Thus some patients with mutations in TMEM67 have been diagnosed with Joubert syndrome (JBT6) or with nephronophthisis (NPHP11)." (PMID 28487520, 2017). "Two unrelated patients with Joubert syndrome (1:34 and 5:38) harbored a compound heterozygous known pathogenic variant and the same missense variant of unknown significance (c.[628T>C] p.[Ser210Pro]) in TMEM67, suggesting a possible founder effect." (PMID 29974258, 2018). "It is reported that kidney disease affects up to 1/3 of patients with Joubert syndrome and is more common in those with pathogenic variants in CEP290, TMEM67 and AHI1 genes." (PMID 35858853, 2022). "Indeed, the authors present data to suggest that WNT/β-catenin signaling is reduced in Tmem67-/- embryonic fibroblasts from embryos with Joubert syndrome-like phenotypes." (PMID 24027500, 2013). "TMEM67 (TMEM67−/−) knock-out animals recapitulate several features of MKS, Joubert syndrome, and Rhyns syndrome in humans and correlate with an aberrant increase in Wnt/β-catenin signaling both in vitro and in vivo." (PMID 36982349, 2023).
Meckel Gruber syndrome (16 papers, 2013 to 2025). "Case #119 was clinically diagnosed with Meckel syndrome, an autosomal recessive disorder; however, the initial analysis identified a maternally inherited stop‐gain variant in TMEM67 [NM_153704.6: c.2440G>T(p.Glu814*)]." (PMID 40078074, 2025). "Variants including the intronic region were evaluated using a gene list associated with Meckel syndrome in this step, leading to the identification of an intronic variant in TMEM67 [NM_153704.6, c.2100 + 3A>G]." (PMID 40078074, 2025). "Second, a novel TMEM67 intron variant associated with Meckel syndrome was detected." (PMID 40078074, 2025). "Biallelic truncating pathogenic variants in TMEM67 (MKS3) commonly lead to Meckel syndrome (MKS3, OMIM #607361); however, “milder” TMEM67 allelic combinations (e.g., biallelic missense variants) lead to less severe phenotypic presentations such as JS or isolated NPHP." (PMID 38292052, 2023). "Mutations in human genes have been associated with Cenani–Lenz syndactyly (LRP4) and Meckel syndrome types 1–5 (MKS1, TMEM67, TMEM67, CEP290, and RPGRIP1L) for which several zebrafish models have been generated." (PMID 34490030, 2021). "Meckel syndrome (MKS) is an inherited autosomal recessive hepatorenal fibrocystic syndrome, caused by mutations in TMEM67, characterized by occipital encephalocoele, renal cysts, hepatic fibrosis, and polydactyly." (PMID 28487520, 2017). "In addition, defects in the Tmem67 gene resulted in Meckel syndrome type 3, Joubert syndrome type 6, and nephronophthisis 11, which show many clinical phenotypic similarities, including hepatic fibrosis." (PMID 23555558, 2013). "Besides, a model of triallelic inheritance of BBS genes was suggested for Bardet-Biedl syndrome, digenic inheritance of unlinked ROM1 and RDS loci was described for retinitis pigmentosa, and digenic trans-heterozygous inheritance of KIF14 and TMEM67 genes—for Meckel Gruber syndrome." (PMID 39180133, 2024).
liver fibrosis (10 papers, 2013 to 2025). "In the UW cohort, 34 patients had colobomas and 12 of them carried mutations in TMEM67 and also presented associated liver fibrosis, a correlation which remained statistically significant even after Bonferroni correction (OR 22.9, CIs 8.6–61.1)." (PMID 35238134, 2022). "The constantly high MNI ranking of Tmem67 from 2 to 12 weeks associated with a HFD suggests that Tmem67 might participate in the development of hepatic fibrosis." (PMID 23555558, 2013). "In two early studies, we reported chorio‐retinal or optic nerve colobomas in about 55% of patients with TMEM67‐related JS, all with liver fibrosis." (PMID 35238134, 2022). "To date, liver involvement, including liver fibrosis (main feature), hepatomegaly, and the elevation of liver enzymes, is found in about 70%–80% of TMEM67-related JS, representing the strongest gene–phenotype association among all JS types." (PMID 36468023, 2022). "Biallelic TMEM67 mutations are known to cause Joubert/Meckel syndrome or nephronopthisis with hepatic fibrosis, but have never been found in isolated hepatic fibrosis." (PMID 28680603, 2017). "Interestingly, not all patients with PKHD1 and TMEM67 variants showed elastographic signs of liver fibrosis." (PMID 40247009, 2025).
Renal cyst (8 papers, 2011 to 2023). A fluid filled sac in the kidney. "The renal consequence of the TMEM67 mutation presented as severely cystic kidneys in the homozygous pups while both heterozygous and WT animals had normal kidneys." (PMID 30705305, 2019). "Transmembrane protein 67 (TMEM67) is mutated in Meckel Gruber Syndrome type 3 (MKS3) resulting in a pleiotropic phenotype with hydrocephalus and renal cystic disease in both humans and rodent models." (PMID 30705305, 2019). "The third class of severe cystic kidney disease is marked by extensive cysts throughout the kidneys (Tmem67)." (PMID 27002738, 2016).
Hydrocephalus (7 papers, 2011 to 2023). Hydrocephalus is an active distension of the ventricular system of the brain resulting from inadequate passage of CSF from its point of production within the cerebral ventricles to its point of absorption into the systemic circulation. "Is important to note that this condition has been closely related to a transmembrane protein 67 (TMEM67) mutation, thanks to which a hydrocephalus model has been implemented in Wistar rats." (PMID 37629571, 2023). "Animals with TMEM67 heterozygous mutations manifest slowly progressing hydrocephalus, observed during the postnatal period and continuing into adulthood." (PMID 30705305, 2019). "In the Tmem67–/– genetic model of communicating hydrocephalus, we have shown that 2 different TRPV4 antagonists inhibit the development of ventriculomegaly." (PMID 32938829, 2020). "Much like children with hydrocephalus, the Tmem67–/– rat pups develop megalocephaly (cranial enlargement and doming), a characteristic that can be used to distinguish WT and homozygous animals." (PMID 32938829, 2020). "Tmem67–/– rats develop hydrocephalus that is ameliorated by treatment with 2 different TRPV4 antagonists." (PMID 32938829, 2020). "MRIs conducted to compare WT and heterozygous animals at 8 months of age, when the animals are still healthy, indicated that the hydrocephalus present at P18 is maintained chronically over the life of the TMEM67+/− animals." (PMID 30705305, 2019). "Taken together, the Evans blue dye injection through the cisterna magna visualized in sagittal orientation supports the histological observation in coronal serial sections that communicating hydrocephalus is present in the TMEM67 homozygous mutant rats." (PMID 30705305, 2019). "When stained with a marker for radial glia and migrating neuroblast, the TMEM67 mutant with hydrocephalus displayed an increase of radial distribution of vimentin+ and DCX+ cells in the cerebral cortex as compared to the wild type animals." (PMID 27243144, 2016). "The hydrocephalus in the TMEM67−/− homozygous animals is severe, resulting in cranial doming." (PMID 30705305, 2019). "In addition, the characterization of the TMEM67+/− phenotype elucidates a novel and potentially useful model of more slowly progressing hydrocephalus." (PMID 30705305, 2019). "The Tmem67+/– heterozygous animals have milder, slowly progressing hydrocephalus, no cystic disease, and no overt symptoms of pain or distress until after the first year of life." (PMID 32938829, 2020). "The heterozygous (TMEM67+/−) rats have midline malformations and mild hydrocephalus that does not appear to impair normal physiological functions until after the first year of life." (PMID 30705305, 2019). "Mice lacking Tmem67 show polycystic kidney disease, hydrocephalus, pulmonary hypoplasia, ventricular septal defects, limb dysplasia and brain anomaly including cerebellar hypoplasia." (PMID 28860541, 2017).